FGF23 (fibroblast growth factor 23)
Diseases named in the same sentence as FGF23 in open-access papers (continued):
Sharing a sentence is not in itself a finding about the gene and the disease.
hyperphosphatemia (continued). "The excretory capacity of the kidney for phosphorus is limited at relatively early stages of CKD despite the hormonal compensation of parathyroid hormone (PTH) and fibroblast growth factor 23 (FGF23), contributing to the elevation of serum phosphorus level (i.e., hyperphosphatemia)." (PMID 37242150, 2023). "Fibroblast growth factor 23 (FGF-23) inhibits this transformation through hyperphosphatemia." (PMID 37033238, 2023). "Both hormones increase as kidney function declines, presumably as a response to maintain normal phosphate balance, but when patients reach kidney failure, PTH and FGF23 fail to exert their phosphaturic effects, leading to hyperphosphatemia and further elevations in PTH and FGF23." (PMID 36977891, 2023). "Early in CKD, FGF23 increases to maintain normal blood phosphate levels, while suppressing 1,25-vitamin D. However, this compensatory mechanism ultimately fails, leading to hyperphosphatemia and hyperparathyroidism." (PMID 36862513, 2023). "Hyperphosphatemia and increased calcitriol concentration in the blood stimulate FGF-23 production." (PMID 37889764, 2023). "In addition, considering the FGF23 values increased significantly with the progression of hyperphosphatemia, the use of phosphorus binders is a necessary treatment of CKD-MBD." (PMID 37089720, 2023). "The elevated FGF-23 levels seen in ESRD patients on dialysis decrease after transplantation but may persist high to counteract hyperphosphatemia favored by reduced kidney function." (PMID 36615824, 2022). "Furthermore, the 25OH D deficiency affect the renal α-hydroxylase inhibition leads to depletion of 1,25-dihydroxyvitamin D [1,25(OH)2D] and an accumulation of Fibroblast Growth Factor-23 (FGF-23) leads to hyperphosphatemia." (PMID 35930297, 2022). "Thus, the relative contribution to the cardiovascular disease burden of progressive CKD per se, hyperphosphatemia, increased FGF-23 and decreased αKlotho levels, and changes in PTH and 1,25(OH)2D need detailed clarification." (PMID 35511366, 2022). "Finally, the decrease in renal function stimulates the production of fibroblast growth factor 23 (FGF23) by osteocytes under the influence of hyperphosphatemia, which in turn inhibits the synthesis of calcitriol." (PMID 35323709, 2022). "Hyperphosphatemia stimulates the synthesis of FGF23 by osteocytes." (PMID 35872985, 2022). "Thus, Tmem174, a strongly correlated molecule with NaPi2a in the GCNs, is thought to be involved in the regulation of NaPi2a by PTH and FGF23 in the kidney and the prevention of hyperphosphatemia in response to a high dietary Pi load." (PMID 35428804, 2022). "Moreover, in that same study, parathyroidectomy before the onset of CKD completely abolished the FGF23 increment, even in a subsequent setting of hyperphosphatemia." (PMID 35629904, 2022). "However, since FGF23 goes up early in CKD prior to the onset of hyperphosphatemia or hyperparathyroidism, other factors including inflammation are also effective." (PMID 35084563, 2022). "Hyperphosphatemia results in increased secretion of FGF23 from bone." (PMID 36615023, 2022). "Previous studies showed a high prevalence of HFpEF in patients with MHD, and several renal factors including the activation of the RAAS, anemia, hyperphosphatemia, increased levels of FGF-23, and uremic toxins have impact on the HFpEF, which lead to HFpEF being more prevalent in patients with MHD." (PMID 36440034, 2022). "Similarly, bone mineral disorders, altered fibroblast growth factor 23 (FGF23), low vitamin-D levels and hyperphosphatemia all impinge upon microvascular dysfunction, thereby triggering or worsening subclinical atherosclerosis." (PMID 35888609, 2022). "Interestingly, Fgf23, a bone-derived hormone produced by osteocytes and osteoblasts in response to hyperphosphatemia, were remarkably increased in nephrectomized BKO mice following PBS intake." (PMID 35622784, 2022).
hyperphosphatemia (continued). "Despite the fact that no phosphate sensor has yet been identified, most authors agreed that, in CKD, the reduced nephron mass causes a decreased renal phosphate excretion that leads to increased FGF23 secretion from the bone to compensate for hyperphosphatemia." (PMID 36615023, 2022). "The klotho (Kl–/–) and/or Fgf23 (Fgf23–/–) knockout mice exhibit many key aspects associated with human CAVD including, premature aging, kidney disease, increased serum phosphate levels (i.e., hyperphosphatemia), and increased osteogenic gene expression." (PMID 35928937, 2022). "Lack of klotho in humans or mice leads to severe hyperphosphatemia, increased 1,25(OH)2D and calcium levels, similar to FGF-23 deficiency." (PMID 36246903, 2022). "Therefore, Fgf23 is probably a key regulator of mineral metabolism in CKD thalassemic mice during hyperphosphatemia." (PMID 35622784, 2022). "Therefore, in the setting of phosphate loading or hyperphosphatemia, an increase in circulating FGF23 levels directly induces phosphate excretion and indirectly reduces dietary phosphate absorption, thus maintaining normal circulating phosphate concentrations." (PMID 35237863, 2022). "Ultimately, high dietary Pi as well as PTH and FGF23 (both hormones produced in states of hyperphosphatemia or upon ingestion of Pi-rich diets) reduce renal reabsorption of Pi by downregulating the expression of cotransporters, whereas low dietary Pi triggers the opposite effects." (PMID 36074191, 2022). "Proteinuria may also act with hyperphosphatemia to increase the risk of ASCVD, which involve the NaPi-IIa, fibroblast growth factor 23, and klotho." (PMID 36369936, 2022). "Therefore, PTH and FGF‐23 exert their harmonious effects in the regulation of plasma Ca2+ levels by preventing hyperphosphatemia and hypermagnesemia." (PMID 35385223, 2022). "Systemic FGF-23 levels rapidly increase as renal function declines, and this occurs before an increase in other markers, such as parathyroid hormone, vitamin D or even phosphorus, likely as a compensatory mechanism to prevent hyperphosphatemia after ARF." (PMID 35216382, 2022). "Adaptation to low and high phosphate diet were similar in Dnase1−/− and Dnase1+/+ mice, and loss of Dnase1 gene expression did not rescue hyperphosphatemia in Fgf23−/− mice." (PMID 33731726, 2021). "Moreover, our results suggest that the period before phosphate accumulation becomes apparent as hyperphosphatemia was shorter in dogs with increased FGF‐23 concentrations." (PMID 34418162, 2021). "FGF-23 increases early in CKD to prevent hyperphosphataemia." (PMID 33974225, 2021). "As the renal function declines, the ability of the kidneys to appropriately excrete a phosphate load is reduced leading to hyperphosphatemia, elevated parathyroid hormone (PTH), and decreased calcitriol with the associated elevations in the levels of fibroblast growth factor-23 (FGF-23)." (PMID 34722580, 2021). "It is therefore possible that the observed link between hyperphosphataemia and renal interstitial fibrosis may be attributable to some other mechanism, such as resultant increases in the phosphaturic hormones FGF-23 and PTH." (PMID 33375963, 2021). "Therefore, the suppression of renal 1,25(OH)2D production makes FGF23 a more effective hormone for counteracting hyperphosphatemia compared with PTH." (PMID 34950827, 2021). "Especially, pro-inflammatory responses mediating hyperphosphatemia-related development of vascular calcification as well as FGF23 as a critical factor in the interplay between inflammation and cardiovascular alterations, beyond its phosphaturic effects, are addressed." (PMID 33416083, 2021). "Other well described factors involved in the process are: hyperphosphatemia, high parathyroid hormone (PTH) serum levels, vitamin D deficiency, elevated fibroblast growth factor 23 (FGF23) plasma levels, in addition to the presence of adenosylhomocysteine, hypervolemia, and anemia, among others." (PMID 34822562, 2021).
hyperphosphatemia (continued). "Phosphate load may lead to increased fibroblast growth factor 23, decreased vitamin D, increased intact parathyroid hormone, and decreased klotho; such a vicious cycle is likely activated even before hyperphosphatemia occurs." (PMID 33459122, 2021). "Increased FGF‐23 concentration in normophosphatemic dogs with CKD was associated with significant risk of development of hyperphosphatemia, independent of CKD stage, and of the progression of CKD." (PMID 34418162, 2021). "If correct, FGF‐23 may be a useful marker of when to initiate a phosphate‐restricted diet to prevent the development of hyperphosphatemia." (PMID 34418162, 2021). "Future research focusing on whether interventions that decrease FGF‐23 secretion will slow the development of hyperphosphatemia and CKD progression is needed." (PMID 34418162, 2021). "Initially, membrane bound renal klotho was considered, exclusively, a high affinity receptor for circulating FGF23 and, therefore, essential for FGF23 phosphaturic actions that attenuate the pro-aging features of hyperphosphatemia: SHPT, systemic inflammation, vascular calcification." (PMID 34950686, 2021). "Hence, FGF23 elevation is caused by high levels of PTH or 1,25(OH)2D3, as well as hyperphosphatemia and hypercalcemia, but the mechanisms of molecular regulation and time effects are not clear." (PMID 34360805, 2021). "Furthermore, according to the literature, imbalance in the FGF-23-Klotho pathway and its consequent hyperphosphatemia is connected to the progression of CKD." (PMID 35056905, 2021). "On the other hand, Familiar Tumor Calcinosis (FTC), a rare autosomal recessive disorder, is a mirror image of FGF23 related hypophosphatemic diseases, featured by hyperphosphatemia, inappropriately elevated 1,25(OH)2D3and PTH levels and ectopic calcified masses." (PMID 34068220, 2021). "Hyperphosphataemia contributes to arterial medial calcification by inducing an osteogenic phenotype change of vascular smooth muscle cells.S39 Phosphate balance is regulated by fibroblast growth factor-23 (FGF-23), a protein secreted primarily by bone tissue." (PMID 31511306, 2020). "Whole-nephron deletion of Klotho in mice results in renal FGF23 resistance, characterized by hypervitaminosis D, hyperphosphatemia, and other phenotypes that may resemble premature aging." (PMID 32982979, 2020). "Recently, FGF23 as a phosphate-regulating hormone has been discovered by the studies on rare hypophosphatemic disorder, whereas Klotho, which subsequently turns out to be a co-receptor for FGF23, is identified in a mouse model showing hyperphosphatemia and multiple aging-like traits." (PMID 33708111, 2020). "Our study revealed that the elevated level of FGF-23 went ahead hyperphosphatemia and elevated PTH." (PMID 33379157, 2020). "Klotho is a bona fide longevity gene that, if inactivated, generates a phenotype identical to that of FGF23-null mice, characterized by premature aging, decreased lifespan, elevated 25(OH)D, hyperphosphatemia, ectopic calcification, skin and muscle atrophy, osteoporosis, and hearing loss." (PMID 32899460, 2020). "Chronic inflammation, anaemia, hypoalbuminaemia, hyperphosphataemia, arterial hypertension, and/or arterial stiffness, and high serum fibroblast growth factor 23 (FGF-23) levels were suggested as contributing factors for LVH in patients with CKD not undergoing dialysis." (PMID 33009458, 2020). "Other consequences of hyperphosphatemia are high levels of fibroblast growth factor 23 (FGF23), which is a hormone involved in phosphate and vitamin D regulation and disruption of bone metabolism, leading to secondary hyperparathyroidism, renal osteodystrophy, and metabolic bone disease (CKD-MBD)." (PMID 33121062, 2020).
hyperphosphatemia (continued). "In spite of the severely decreased renal function in our patient, the reduction of functional KL with the consequent insensitivity to the action of FGF23 could partially explain the state of persistent and resistant hyperphosphatemia described in the patient." (PMID 31013726, 2019). "Consequently, hyperphosphatemia manifests, although FGF23 levels increase up to 100–1000-fold in patients on hemodialysis." (PMID 31698866, 2019). "Thus, a detailed understanding of the molecular insights of FGF23 and hyperphosphatemia in the development of cardiovascular disease is essential to develop successful therapeutic strategies." (PMID 31698866, 2019). "This would be in line with the concept that FGF23 may be a mediator of phosphate toxicity, at least on the heart in a setting of CKD, and in that scenario targeting FGF23 by any means, besides addressing hyperphosphatemia, would be beneficial." (PMID 31505780, 2019). "Hyperphosphatemia results from a positive phosphorus balance in renal patients, which results in a compensatory secondary hyperparathyroidism and an increase in fibroblast growth factor-23 levels (FGF-23)." (PMID 31167346, 2019). "Col4a3−/− mice demonstrated impaired kidney function, reduced bone DMP1 expression, reduced bone mass, altered osteocyte morphology and connectivity, increased osteocyte apoptosis, increased serum FGF23, hyperphosphatemia, left ventricular hypertrophy (LVH), and reduced survival." (PMID 31044094, 2019). "Clearly, high circulating calcitriol levels caused by loss of FGF23 function are not detrimental per se, but the toxicity is rather greatly caused by hyperphosphatemia and hypercalcemia, both induced by increased vitamin D activity." (PMID 30970562, 2019). "However, as only some animal models examined with elevated FGF23 developed renal injury or hyperphosphatemia, while all animal models displayed increased serum concentrations of cytokines, it is feasible FGF23 acts as a major driver of inflammation in CKD." (PMID 31461904, 2019). "In humans, increased FGF23 levels appear before a detectable rise in PTH and hyperphosphataemia, suggesting that an increase in FGF23 may be the earliest sign of disordered mineral metabolism in CKD." (PMID 30393837, 2019). "Notably, phosphate retention, progressive hyperphosphatemia, rising FGF23 levels and low Klotho expression collectively are observed in human patients with advancing CKD and has been associated with progressive age-associated cardiovascular alterations." (PMID 31546756, 2019). "However, injection of a mutated soluble Klotho isoform lacking the FGF receptor binding arm resulted in a striking downregulation of FGF23 target genes in the kidney with the development of hyperphosphatemia." (PMID 31546756, 2019). "Interestingly, dietary phosphate restriction, a strategy normally used in CKD patients with hyperphosphatemia, can reduce FGF23 levels thereby potentially preventing cardiotoxicity of FGF23." (PMID 30200452, 2018). "Decreasing eGFR is associated with secondary hyperparathyroidism, abnormalities in 1,25-dihydroxy vitamin D synthesis, hyperphosphatemia, chronic metabolic acidosis, and elevated sclerotia and/or fibroblast growth factor 23 (FGF-23) levels, which results in the bone absorption and formation." (PMID 29320555, 2018). "Mice lacking Klotho or FGF23 exhibit a premature aging syndrome associated with abnormal mineral metabolism characterized by hyperphosphatemia, hypercalcemia, and hypervitaminosis D." (PMID 30271655, 2018). "In conclusion, there is a need for a paradigm shift in the treatment of hyperphosphatemia, and new therapeutic options that antagonize the deleterious effects of FGF23 and enhance the protective effects of soluble αKlotho may emerge in the future." (PMID 30087898, 2018). "In addition, hyperphosphatemia is associated with VC in animal models of CKD, and mice with targeted deletion of FGF23 or klotho show hyperphosphatemia and VC." (PMID 29922171, 2018).
hyperphosphatemia (continued). "Since the FGF23 KO mice and the Klotho mice exhibited severe muscle wasting, we wondered whether hyperphosphatemia could directly affect the skeletal muscle cells, leading to sarcopenia." (PMID 30271655, 2018). "Hyperphosphatemia can induce osteocytes and osteoblasts to express FGF-23 and subsequently reduces phosphate reabsorption by inhibiting NaPi-IIa activity directly and indirectly by inhibiting renal CYP27B1 expression to lower blood 1,25D level, then reduces intestinal phosphate absorption." (PMID 30513912, 2018). "There is also no data demonstrating an increased cardiovascular risk or a higher prevalence of LVH in patients with FGF23-related hypophosphatemic diseases, but this is not expected since there is no hyperphosphatemia and CKD." (PMID 30087898, 2018). "In addition, FGF23-deficient mice exhibit a failure to grow, bone lesions, a short lifespan, hyperphosphatemia, and high blood vitamin D levels, suggesting that FGF23 is a hormone regulator of P metabolism." (PMID 29518087, 2018). "Eight weeks postsurgery, WT CKD mice were characterized by reduced bone mineral density at the axial and appendicular skeleton, hyperphosphatemia, secondary hyperparathyroidism, increased serum intact Fgf23, and impaired bone mineralization as evidenced by bone histomorphometry." (PMID 29942284, 2018). "SFRP4 has a phosphaturic action similar to that of FGF-23,46 and its downregulation may be relevant to the persistent hyperphosphatemia seen in this patient." (PMID 28326223, 2017). "Increased serum levels of FGF-23 in renal failure could also be due to a direct physiologic response to hyperphosphatemia." (PMID 28828171, 2017). "Thus, sKl deficiency is an important risk factor for CKD-associated cardiac hypertrophy independently of the effects of hyperphosphatemia and FGF23." (PMID 29250031, 2017). "Fgfr1PT-cKO mice exhibited an increase in sodium-dependent phosphate co-transporter expression, hyperphosphatemia, and refractoriness to the phosphaturic actions of FGF-23, consistent with a direct role of FGFR1 in mediating the proximal tubular phosphate responses to FGF-23." (PMID 26839958, 2016). "Moreover, hyperphosphatemia also stimulates FGF23 secretion, resulting in an increased renal P excretion, a reduced intestinal P absorption and decreased plasma PTH and calcitriol concentrations." (PMID 26870965, 2016). "However dissociated hyperphosphatemia and low serum FGF-23 concentrations have been observed in experimentally parathyoridectomized rats." (PMID 26186634, 2015). "However, in the PTX+CKD rats in our study, a low mean serum FGF-23 level was noted despite hyperphosphatemia, which was likely related to low mean circulating PTH levels." (PMID 26186634, 2015). "Furthermore, the recent reports noted that hyperphosphatemia plays a pivotal role in promoting vascular calcification by modifying Klotho-FGF23 axis." (PMID 26367531, 2015). "In humans with reduced FGF23 activity, familial tumoral calcinosis, hyperphosphatemia may present as early as 21 months old, indicating that FGF23 is important in phosphate handling when most episodes of otitis media develop." (PMID 25243481, 2014). "As CKD progresses, compensation for the elevations in parathyroid hormone (PTH) and fibroblast growth factor-23 (FGF-23) and for reduced levels of 1,25(OH)2D3 becomes inadequate, resulting in hyperphosphatemia, abnormal bone disorders, and extra-skeletal calcification." (PMID 24587915, 2014). "Hyperphosphatemia in turn stimulates FGF23 secretion from the skeleton." (PMID 24797667, 2014). "When hyperphosphatemia occurred in the HD patients, the serum FGF-23 level elevated, 1,25(OH)2D3 level decreased, and renin-angiotensin-aldosterone system activation, all may deteriorate the systemic inflammation." (PMID 24558316, 2014). "FGF23 is a protective hormone against the untoward biological consequences of hyperphosphatemia." (PMID 24797667, 2014).